BRCA1 (BRCA1 DNA repair associated)
Diseases named in the same sentence as BRCA1 in open-access papers (continued):
Sharing a sentence is not in itself a finding about the gene and the disease.
Fanconi anemia (continued). "Cells defective in different DNA repair actors, such as ataxia telangiectasia, Fanconi anemia, and Cockayne and Bloom syndrome cells or BRCA1-defective cells, commonly show elevated levels of endogenous ROS." (PMID 27135742, 2016). "The most famous example of this is the synthetic lethality relationship between the BRCA1/2 gene in the Fanconi Anemia pathways and PARP." (PMID 27438146, 2016). "The FANCJ protein is one of the Fanconi anemia (FA) gene products, and its interaction with the tumor suppressor BRCA1 is required for DNA double-strand break (DSB) repair." (PMID 22968820, 2013). "Conversely several components within the Fanconi anemia network, interact with BRCA1 (directly or indirectly) and participate in BRCA1-dependent DNA repair of DSBs, including FANCJ (=BACH1), FANCN (=PALB2), and FANCD1 (BRCA2)." (PMID 23802008, 2013). "In another recent study, fibroblasts of BRCA1 and BRCA2 mutation carriers, a BRCA2-deficient fanconi anemia patient and normal individuals were exposed to mammography X-rays and chromosomal anomalies were assessed." (PMID 23936236, 2013). "The protein product of the Fanconi anaemia gene PALB2 (FANCN) serves as a bridge between BRCA1 and BRCA2." (PMID 23587053, 2013). "BRCA1 has been shown to have a potential role in Fanconi anemia through its role in the colocalization of FANCD2 protein." (PMID 22761553, 2012). "Somatic BRCA1 data can also be compared to that for the hereditary disease Fanconi anemia because BRCA1 interacts with the Fanconi protein FANCJ." (PMID 17683622, 2007). "Importantly, BRCA1, BRCA2, and several associated genes — particularly members of the Fanconi anemia gene family — are transcriptionally regulated by the DREAM complex." (PMID 40841483, 2026). "Moreover, 14% of the patients included in this study harbored deleterious mutations in Fanconi anemia genes (FANCA, FANCD2, FANCF, FANCG FANCI and FANCL) and in WRN, which have been reported to interact with BRCA1." (PMID 38184614, 2024). "Furthermore, in addition to its’ role in homologous recombination DNA repair, BRCA1 is a downstream component of the Fanconi anaemia pathway responsible for inter-strand crosslink repair and replication stress response." (PMID 39084071, 2024). "Other predisposition syndromes, such as BRCA1-/BRCA2-related tumor predisposition syndrome, Fanconi anemia and Li Fraumeni syndromes, are sensitive to both IR and chemicals, as they interfere with different repair pathways that are also responsible for chemicals." (PMID 36899955, 2023). "Besides, there were interactions between breast cancer susceptibility protein 1 or 2 (BRCA1 or BRCA 2) mutations and Fanconi Anemia proteins in the homologous recombination pathway." (PMID 35784751, 2022). "Almost half of HGSOC tumors are characterized by homologous recombination (HR) deficiency through germline or somatic mutations in BRCA1/2 (20%), BRCA1 hypermethylation (11%), and/or dysregulation of other HR genes including PTEN, ATM or ATR, RAD51C, EMSY and Fanconi anemia genes." (PMID 33669749, 2021). "Mechanistically, we find that multiple genes in the homologous recombination and Fanconi anemia repair pathways, including BRCA1, FANCD2, and RAD51, are dependent on Wnt/β‐catenin signaling in Wnt‐high cancers, and treatment with a PORCN inhibitor creates a BRCA‐like state." (PMID 33660437, 2021).
Fanconi anemia (continued). "We found that the knockdown of TAPIRs leads to the suppression of genes essential for the DNA-damage response, as there are BRCA1 (breast cancer 1, early-onset), CHEK1 (Checkpoint kinase 1), CLSPN (Claspin), and genes encoding proteins of the Fanconi anemia pathway." (PMID 32365858, 2020). "Secondly, TIGAR KD induces “BRCAness” by downregulation of BRCA1 and the Fanconi anemia pathway." (PMID 31508509, 2019). "The gene panel used for the analyses of the DNA of 41 patients by massive sequencing detected the presence of numerous variants in genes coding for proteins involved in DNA repair such as ATM, ATR, BRCA1, BRCA2 and several genes of the FANC complex, mutated in Fanconi Anemia." (PMID 30995915, 2019). "BRCA1, BRCA2, and PALB2 were among the genes associated with the Fanconi anemia pathway." (PMID 30719229, 2019). "Reversed forks are protected through the actions of a number of factors including the tumour suppressor genes BRCA1 (BRCA1, DNA repair associated) and BRCA2 (BRCA2, DNA repair associated), as well as other components of the homologous recombination and Fanconi anaemia (FA) repair pathways." (PMID 30525090, 2018). "Mutations in PTEN, SOX2 and NOTCH1, which are also frequently associated with SCLC, and BRCA1/2 or other known Fanconi anaemia genes were also not detected." (PMID 29387807, 2017). "PALB2 is a partner of BRCA1/2 and is involved in Fanconi anemia." (PMID 28027327, 2016). "Finally, many cells that are affected by the DNA damage response (DDR), such as ataxia telangiectasia, Fanconi anemia, Cockayne syndrome or Bloom syndrome cells, or defective in BRCA1 exhibit elevated levels of endogenous ROS." (PMID 27135742, 2016). "Recent study has demonstrated that BRCA1 protein is also a critical component of the Fanconi pathway and that BRCA1 may itself be a Fanconi anemia gene." (PMID 25429431, 2014). "In addition to BRCA1/2 deficiency, the amplification of EMSY and deficiencies in PTEN, Fanconi Anemia genes, RAD genes and DNA repair genes involved in HR (including ATM, ATR and CHEK1/2) have also been identified to cause HR defects in human cancer." (PMID 25437005, 2014). "Fanconi anemia (FA) syndrome, together with other genetic disorders and breast cancer 1 (BRCA1), a hereditary breast-ovarian cancer syndrome, are striking examples that the loss of genomic stability caused by a deficiency of the DNA repair pathways can confer an increased susceptibility to cancer." (PMID 24260277, 2013). "Indeed, regulation of Rad51, essential for homologous recombination as well as breast cancer 1 (Brca1) and Fanconi anemia, complementation group A (Fanca) that build DNA repair complexes were found to be repressed." (PMID 21152443, 2010). "Likewise, biallelic BRCA1, BRCA2, BRIP1, PALB2 and RAD51C mutations lead to Fanconi anemia." (PMID 36292468, 2022). "Fanconi anaemia can be inherited in an autosomal recessive manner, most commonly due to biallelic, pathogenic variants in FANCA, and less frequently due to biallelic variants in any of at least twenty genes, which include BRCA2, PALB2, RAD51C, and very rarely, BRCA1." (PMID 34771713, 2021). "Although they mainly affect the BRCA1 and BRCA2 genes, they have been detected in other genes such as RAD51C hypermethylation (RAD51 paralog C), ATM (ataxia telangiectasia mutated serine-protein kinase gene), or ATR mutations, and mutations of the HR interacting Fanconi anemia gene." (PMID 34638899, 2021).
Fanconi anemia (continued). "BRCA1 was investigated due to its role in homologous DNA repair, and as part of the Fanconi Anemia/BRCA pathway, with the known genetic predisposition of patients with Fanconi Anemia to develop malignancies including oral tongue and oral cavity squamous cell carcinomas." (PMID 25859283, 2014). "An additional connection to Fanconi anemia may be through interaction with BRCA1." (PMID 22761553, 2012). "This pathway involves multiple proteins, including BRCA1, BRCA2, proteins of the MRN complex, CtIP, RAD51, ATM, H2AX, PALB2, RPA, RAD52, and proteins of the Fanconi anemia pathway." (PMID 38236558, 2024). "The Fanconi anemia (FA) repair pathway promotes the excision of ICLs using at least 22 FANC proteins, including FANCS/BRCA1 and FANCD1/BRCA2." (PMID 38714348, 2024). "BRCA1 and FANCJ are known to be involved in DNA double-strand break repair by homologous recombination, fork protection, and Fanconi anemia pathways." (PMID 38521768, 2024). "Approximately half of high-grade serous epithelial ovarian cancers incur alterations in genes of homologous recombination (BRCA1, BRCA2, RAD51C, Fanconi anemia genes), and the rest incur alterations in other DNA repair pathways at high frequencies." (PMID 37684587, 2023). "BRCA1 and BRCA2 are part of the BRCA–Fanconi anemia pathway, and other Fanconi genes, such as BRIP1 and RAD51C, have also been associated with an inherited risk of OC." (PMID 36555431, 2022). "Upregulation of the fanconi anemia pathway components such as RAD51 and BRCA1/2, leads to homologous recombination restoration and drug resistance." (PMID 35874683, 2022). "Previous studies showed that DDR genes, including BRCA1, BRCA2, and multiple Fanconi anemia genes, were particularly sensitive to aberrant intronic polyadenylation events." (PMID 34330913, 2021). "The components of the Fanconi anemia (FA) and HR pathways include RAD51 (FANCR), FANCD2, BRCA1 (FANCS) and (FANCD1), and these pathways were shown to coordinately suppress nascent DNA degradation." (PMID 34144707, 2021). "As RAD51 is the downstream effector protein of the Fanconi anemia-BRCA pathway (FA-BRCA) which mediates HR, we further analyzed BRCA1 levels in these cells." (PMID 31492187, 2019). "Both BRCA1 (FANCS) and BRCA2 (FANCD1) are part of the Fanconi Anemia (FA) mediated DSB repair pathway." (PMID 31225499, 2019). "Several presumably somatic variants were found in DNA repair genes which share homologous DNA repair function with BRCA1 and BRCA2 and are in the same Fanconi anemia pathway." (PMID 31346352, 2019). "In this study, 88% of patients with alteration of DNA repair genes (BRCA1&2, ATM, Fanconi anemia genes) had an objective response." (PMID 28978184, 2017). "HR operates during the S and G2 phases of the cell cycle and relies on many proteins including BRCA1 and BRCA2, proteins of the MNR complex (MRE11/RAD50/NBS1), CtIP, MRE11, RAD51, ATM, H2AX, PALB2, RPA, RAD52 and proteins of the Fanconi anemia pathway." (PMID 28250960, 2017). "Defects in major tumor suppressor genes BRCA1 and BRCA2, and a subset of the Fanconi Anemia genes have been shown to result in deregulation in fork remodeling, and most prominently, loss of kilobases of nascent DNA from stalled replication forks." (PMID 29355244, 2017). "Again, DNA repair and cell-cycle-related genes (e.g., Fanca, Brca1, Eme1, Cdc6, Cdc7, Chek1) are enriched (e.g., KEGG terms: Fanconi anemia pathway, homologous recombination, cell cycle, Base excision repair)." (PMID 28638111, 2017). "In support of this, R-loops accumulate in cells depleted of the BRCA1, BRCA2 or the Fanconi anemia (FA) DNA repair factors, indicating that they play an active role in R-loop dissolution." (PMID 28653981, 2017).
Fanconi anemia (continued). "BRCA1 is critically involved with the Fanconi anemia proteins in repairing DNA damage, whereas BRCA2 is itself a Fanconi anemia protein." (PMID 26528434, 2015). "In hereditary cancers, the genomic instability has been linked to defects in genes involved in the repair of DSBs via HR, such as BRCA1/2, RAD50 and the Fanconi anaemia gene." (PMID 25437005, 2014). "The BRCA/FA pathway is a key part of the homologous recombination DNA repair machinery and includes the BRCA1 and BRCA2 genes as well as members of the Fanconi anaemia complementation group." (PMID 23587053, 2013). "Ube2W has been shown to be responsible for the mono-ubiquitylation of BRCA1 (breast cancer early-onset 1), Fanconi's anaemia proteins FANCL (Fanconi's anaemia, complementation group L) and FANCD2 (Fanconi's anaemia, complementation group D2) and CHIP." (PMID 23560854, 2013). "As an example of interactions between Fanconi anemia proteins and BRCA1/2 proteins, the Fanconi anemia protein FANCJ forms an essential complex with BRCA1." (PMID 17683622, 2007). "BRCA1 and BRCA2 gene products are placed within a sequence encompassing the MRE11, Rad50 and NBS1 complex (MRN complex), ATM, CHEK2, BRCA1, BRCA2, and Fanconi anemia proteins." (PMID 17683622, 2007). "In fact, loss of most genes involved in DNA damage checkpoints or DNA damage repair, such as ATM, ATR, BRCA1, BRCA2, Fanconi anemia genes, lead to increased sensitivity to genotoxic agents." (PMID 15494723, 2004). "Notably, BRCA1 (FANCS) and BRCA2 (FANCD1) belong to the Fanconi anemia complementation group, which preserves genomic integrity by repairing DNA interstrand crosslinks and stabilizing replication forks." (PMID 40841483, 2026). "Since the detection rate of biallelic pathogenic variants is extremely low, including ataxia telangiectasia for ATM and Fanconi anemia for BRCA1 and BRCA2, we did not describe the autosomal recessive mode of inheritance in the Fact Sheet, except for MUTYH." (PMID 40183848, 2025). "FANCS/BRCA1, FANCD1/BRCA2, FANCN/PALB2 and FANCO/RAD51C are Fanconi anemia (FA) genes." (PMID 37566130, 2023). "BRCA1 and BRCA2 (also present in the global downregulated network) are tumor suppressor genes belonging to the homologous recombination and Fanconi anemia pathways, involved in preserving chromosomal stability, regulating cell response to double-stranded DNA breaks and participating in DNA repair." (PMID 34660619, 2021). "Other defects in homologous recombination repair genes, such as EMSY, RAD51, ATM, ATR, Fanconi anemia, BARD1, BRIP1, PALB2, RB1, NF1, CDKN2A, and the suppression of BRCA1 transcriptional activation through gene methylation, are associated with homologous recombination deficiency (HRD)." (PMID 32679669, 2020). "The BRCA1/FANCS and BRCA2/FANCD1 gene products have been found to be involved in DNA double strand-break (DSB) repair and DNA interstrand cross-links (ICLs) repair by homologous recombination (HR) and Fanconi anemia pathway." (PMID 31890056, 2019). "This phenotype was present in cells defective for breast cancer susceptibility genes BRCA1 and BRCA2, or Fanconi Anemia genes FANCD2, or FANCA, but not in the wild type cells." (PMID 29355244, 2017). "Recent evidence indicates that R-loops might also be formed in human cells, for which DNA repair proteins such as BRCA1, BRCA2 and other Fanconi Anemia factors could play a kind of back-up system to remove then." (PMID 27035147, 2016). "Several proteins in the BRCA-Fanconi anemia (FA) pathway, such as FANCJ, BRCA1, and FANCD2, interact with mismatch repair (MMR) pathway factors, but the significance of this link remains unknown." (PMID 24966277, 2014).
Fanconi anemia (continued). "Relationships and critical interactions exist among BRCA1, BRCA2 and Fanconi anemia proteins." (PMID 17683622, 2007). "The Fanconi anaemia (FA) pathway constitutes a central genome maintenance system that orchestrates the repair of DNA interstrand crosslinks (ICLs) through the coordinated monoubiquitination of FANCI and FANCD2, followed by recruitment of repair effectors such as BRCA1, REV1, and ERCC1." (PMID 41486508, 2026). "Efficient repair of PARPi-induced DSBs in S-phase human cells depends on HDR pathways, which require the DNA damage response proteins BRCA1/2, ATM/ATR, Chk1/2, PALB2, and BRIP1; the Fanconi Anemia (FA) proteins; and the HDR proteins that include EXO1, DNA2, and RAD51." (PMID 38714348, 2024). "Moreover, BRCA2′s contribution to the repair of cisplatin-induced interstrand crosslinks is more significant than BRCA1, which is likely attributable to the fact that BRCA2, but not BRCA1, functions in the Fanconi anemia repair pathway." (PMID 21779174, 2011). "In addition, we confirm variants with pathogenic status in BRCA1 and BRCA2 as they were never encountered in homozygosity except in two cases with resulting Fanconi anemia phenotype (NM_ 000059.3:c.7007G > A:p.Arg2336His and NM_000059.3: c.9152delC, p.Pro3051Hisfs*11)." (PMID 27884173, 2016). "Additionally, most chemicals also inhibited IR-induced RAD51 foci formation and DNA double-strand break repair by HR, but generally not BRCA1 foci formation, indicating that they inhibit multiple discrete steps of the DNA damage response and are not specific inhibitors of the Fanconi anemia pathway." (PMID 22537224, 2012).